EIF3H (eukaryotic translation initiation factor 3 subunit H)
Description:
Component of the eukaryotic translation initiation factor 3 (eIF-3) complex, which is required for several steps in the initiation of protein synthesis. The eIF-3 complex associates with the 40S ribosome and facilitates the recruitment of eIF-1, eIF-1A, eIF-2:GTP:methionyl-tRNAi and eIF-5 to form the 43S pre-initiation complex (43S PIC). The eIF-3 complex stimulates mRNA recruitment to the 43S PIC and scanning of the mRNA for AUG recognition. The eIF-3 complex is also required for disassembly and recycling of post-termination ribosomal complexes and subsequently prevents premature joining of the 40S and 60S ribosomal subunits prior to initiation. The eIF-3 complex specifically targets and initiates translation of a subset of mRNAs involved in cell proliferation, including cell cycling, differentiation and apoptosis, and uses different modes of RNA stem-loop binding to exert either translational activation or repression.
Synonyms: EIF3S3; eIF3-gamma; eIF3-p40
Tractability: Small molecule: a structure with a bound ligand is known. PROTAC: UniProt records ubiquitination sites on it; ubiquitination databases record sites on it; its protein half-life has been measured.
Gene: Protein-coding gene on chromosome 8 (116,642,130 to 116,766,925, reverse strand). Ensembl gene ENSG00000147677.
Subcellular location: Cytoplasm
Subcellular location (Human Protein Atlas): Cytosol
Pathways (Reactome):
Metabolism of proteins: Formation of a pool of free 40S subunits; Formation of the ternary complex, and subsequently, the 43S complex; GTP hydrolysis and joining of the 60S ribosomal subunit; L13a-mediated translational silencing of Ceruloplasmin expression; Ribosomal scanning and start codon recognition; Translation initiation complex formation
Gene Ontology:
Molecular function: metal-dependent deubiquitinase activity; protein binding; RNA binding; translation initiation factor activity; metallopeptidase activity; peptidase activity
Biological process: negative regulation of proteasomal ubiquitin-dependent protein catabolic process; translational initiation; formation of cytoplasmic translation initiation complex; regulation of translational initiation; cytoplasmic translational initiation
Cellular component: eukaryotic translation initiation factor 3 complex; extracellular exosome; membrane; cytosol; eukaryotic 43S preinitiation complex; cytoplasm; eukaryotic 48S preinitiation complex; eukaryotic translation initiation factor 3 complex, eIF3m
Genetic constraint (gnomAD): Loss-of-function variants: 25 observed, 43.69 expected, observed/expected ratio (o/e) 0.57, 90% interval 0.42 to 0.8. The upper end of that interval is the gene's LOEUF score, 0.8, which puts it in group 3 of 6, group 1 being the genes least tolerant of losing a copy. Missense variants: 356 observed, 451.57 expected, observed/expected ratio (o/e) 0.79, 90% interval 0.72 to 0.86. Synonymous variants: 165 observed, 160.92 expected, observed/expected ratio (o/e) 1.03, 90% interval 0.9 to 1.17.
Homologues: Orthologues: chimpanzee EIF3H (100% identical), macaque EIF3H (99% identical), dog EIF3H (98% identical), pig EIF3H (98% identical), mouse Eif3h (97% identical), rat Eif3h (97% identical), guinea pig EIF3H (97% identical), rabbit EIF3H (90% identical), tropical clawed frog eif3h (81% identical), Drosophila melanogaster eIF3h (43% identical), Caenorhabditis elegans eif-3.H (39% identical). Paralogues in human: PSMD14 (18% identical), BRCC3 (16% identical), COPS5 (16% identical).
Diseases named in the same sentence as EIF3H in open-access papers:
EIF3H is named in the same sentence as 48 diseases in open-access papers, as found by Europe PMC text mining. Sharing a sentence is not in itself a finding about the gene and the disease. The quoted sentences say what the papers report.
prostate carcinoma (13 papers, 2004 to 2023). A carcinoma that arises from epithelial cells of the prostate gland. "Overexpression of EIF3H is documented in prostate, breast, and liver cancer, and is associated with advanced cancer stage and poor prognosis in prostate cancer." (PMID 27340783, 2016). "High level amplification of the EIF3H has also been associated with advanced stage and poor prognosis prostate cancer." (PMID 20862326, 2010). "Additionally, the levels of eIF3h expression are positively associated with the poor differentiation and aggressive growth of prostate cancer." (PMID 33148274, 2020). "Moreover, amplification of the EIF3H is associated with advanced stage and poor prognosis in prostate cancer." (PMID 32867821, 2020). "Multiple components of the EIF3 are now known to be dysregulated in multiple cancers (EIF3A in breast, cervical, lung and gastric cancers; EIF3B in breast and gastric cancers; EIF3C in testicular cancers; and EIF3H in prostate cancers)." (PMID 35528200, 2022). "It has been observed that eIF3H is often amplified in breast and prostate cancer together with proto-oncogene Myc." (PMID 35574327, 2022). "Elevated eIF3h has been confirmed in 18% of breast cancer, 30% of prostate cancer and 50% of hepatocellular carcinoma." (PMID 33193582, 2020). "Regarding eIF3h, it has been observed to be frequently amplified along with the proto-oncogene Myc in breast and prostate cancer." (PMID 33148274, 2020). "Decreasing EIF3H by siRNA knockdown in breast and prostate cancer cell lines slows cell proliferation and reduces anchorage-independent growth in soft agar." (PMID 27340783, 2016). "For example, eIF3h and eIF4E are frequently overexpressed in advanced prostate cancers, together with increased phosphorylation of eIF4E and eIF4E-BP1, which support increased translation." (PMID 23405127, 2013). "Reduction of eIF3h levels in breast and prostate cancer cell lines by shRNA methods has previously been shown to reduce cell proliferation and anchorage-independent growth in soft agar." (PMID 20862326, 2010). "The expression level of eIF3h is higher in metastatic prostate cancer than in primary prostate cancer, and eIF3h may play an important regulatory role in the translation of specific mRNAs." (PMID 36830614, 2023). "In prostate cancer, elevation of eIF3h positively correlates with tumor stages." (PMID 36830614, 2023). "In addition, the expression level of eIF3H is positively correlated with the poor differentiation and invasive growth of prostate cancer." (PMID 35574327, 2022). "Expression of the EIF3H gene was shown to be significantly upregulated in many human cancers, including non-small cell lung cancer, breast cancer, hepatocellular carcinomas, colorectal cancer, prostate cancer and osteocarcinoma." (PMID 32867821, 2020). "EIF3H usually is overexpressed in prostate cancer and breast cancer." (PMID 22734884, 2012).
colorectal cancer (12 papers, 2010 to 2024). A primary or metastatic malignant neoplasm that affects the colon or rectum. "Based on GWAS Catalog, 6p22.1 region covers TRNAA-UGC which was reported associated with lung adenocarcinoma and 8q23.3 region contains EIF3H which was reported associated with colorectal cancer." (PMID 23469237, 2013). "Here, we report that EIF3H is overexpressed in colorectal cancer (CRC) and correlates with poor prognosis." (PMID 38514606, 2024). "Mechanistically, exosomal circLPAR1 is up-taken by colorectal cancer cells and binds eIF3h, leading to decreased accumulation of BRD4 (bromodomain containing 4), to inhibition of cell proliferation and to invasiveness." (PMID 36831450, 2023). "To confirm the binding affinity of circLPAR1 for eIF3h, we first observed them and identified the colocalization of circLPAR1 and eIF3h in the cytoplasm of colorectal cancer cells." (PMID 35164758, 2022). "Mechanistically, exosomal circLPAR1 expression level led to decreased BRD4 levels because it binds eIF3h and inhibits the METTL3–eIF3h interaction, which remarkably suppressed colorectal cancer development." (PMID 35164758, 2022). "Mechanistically, exosomal circLPAR1 is internalized by colorectal cancer cells and binds eIF3h to reduce METTL3-eIF3h-dependent mRNA translation, thereby inhibiting BRD4 expression and suppressing cellular proliferation, invasion, and migration." (PMID 35164758, 2022). "It has been reported that eIF3 binds to the 5’ untranslated region of a specific set of mRNAs involved in cell growth control, and that the increased expression of EIF3H gene potentiates colorectal cancer growth and invasiveness." (PMID 31546890, 2019). "Exosomal circLPAR1 was internalized and direct binding of eIF3h by exosomal circLPAR1 blocked METTL3-eIF3h binding, inhibited translation of oncogene bromodomain containing 4 (BRD4), and reduced malignant progression of colorectal cancer." (PMID 37152286, 2023). "It was reported that exosomal circLPAR1 could serve as a sponge of eIF3h to inhibit the METTL3–eIF3h interaction and affect BRD4 protein expression, thereby suppressing colorectal cancer development." (PMID 36139074, 2022).
breast carcinoma (11 papers, 2004 to 2022). "Another potential gene biomarker in the CNA dataset is EIF3E, a translation factor associated with breast cancer occurrence which is related to EIF3H." (PMID 35205681, 2022). "We found that high transcript levels of 3 genes – NSMCE2, MAL2 and EIF3H – significantly correlate with worse overall survival in breast cancer patients (Log-rank test, p-value < 0.05)." (PMID 36224576, 2022). "This EIF3H gene was previously discovered with RNA-seq and validated by PCR in breast cancer SK-BR-3 cell line." (PMID 35113898, 2022). "A siRNA screen identifies EIF3H as a driver gene within the 8q23.3 amplicons contributing to cell growth, survival and transformation in breast cancer." (PMID 32867821, 2020). "A recent siRNA screening study identified eight driver genes, including EIF3H, on chromosome 8q23, that regulate the proliferation/survival of clonogenic breast cancer cells." (PMID 27340783, 2016). "Here, we determined that there was not a significant difference in the comparison between the expression of EIF3H and NPI grades, and that up-regulated EIF3I was correlated with a better outcome for patients with breast cancer, which made their function remain controversial." (PMID 35040374, 2022).
hepatocellular carcinoma (8 papers, 2016 to 2025). A malignant tumor that arises from hepatocytes. "The elevated expression of eIF3H is consistently associated with proliferation, invasion, and tumorigenicity in human hepatocellular carcinoma." (PMID 36902316, 2023). "Overexpression of Eif3h was mainly associated with proliferation, invasion, and tumorigenicity in human hepatocellular carcinoma and other types of cancer, but its role with respect to BPA exposure in the hippocampus is still unclear." (PMID 33441873, 2021). "The YTHDF1/EIF3C axis is involved in the invasion process in ovarian cancer; EIF3H participates in the invasion of hepatocellular carcinoma and the EIF4A3/FLOT1 pathway promotes invasion and tumor proliferation in lung adenocarcinoma." (PMID 40705973, 2025). "We studied the role of eukaryotic translation initiation factor 3 subunit H (EIF3H) in hepatocellular carcinoma (HCC) progression." (PMID 27340783, 2016). "The deubiquitinase EIF3H promotes hepatocellular carcinoma progression by stabilizing OGT." (PMID 39715739, 2024). "Also, eIF3h has been found to enhance tumorigenicity, invasion, and proliferation in hepatocellular carcinoma via TGF-β and MAPK pathways, making it a prognostic marker for hepatocellular cancer patients." (PMID 39409166, 2024).
lung adenocarcinoma (5 papers, 2013 to 2025). A carcinoma that arises from the lung and is characterized by the presence of malignant glandular epithelial cells. "In lung adenocarcinoma, eIF3h protein was found up-regulated compared with normal lung tissues and an unfavorable factor promoting the cancer pathogenesis." (PMID 33193582, 2020). "In contrast, one study reported that eIF3h protein was highly expressed in lung adenocarcinoma tissues and that eIF3h overexpression promoted lung adenocarcinoma cell migration and invasion, which further confirmed that eIF3h is an oncogenic factor in lung adenocarcinoma." (PMID 36118041, 2022). "A recent publication in lung adenocarcinoma demonstrated that EIF3H overexpression could also induce EMT signaling pathway." (PMID 32867821, 2020). "In lung adenocarcinoma, EIF3H functions as an oncogene by inducing EMT signaling pathway, which could be inhibited by PDCD4." (PMID 32867821, 2020). "In addition, direct physical and functional interactions between eIF3h and METTL3 have been reported to be required for enhanced translation of oncogenic mRNAs, formation of densely packed polyribosomes and oncogenic transformation of lung adenocarcinoma." (PMID 36118041, 2022).
glioma (4 papers, 2019 to 2023). A benign or malignant brain and spinal cord tumor that arises from glial cells (astrocytes, oligodendrocytes, ependymal cells). "In both the CGGA and TCGA datasets, the expression levels of eIF3d, eIF3e, eIF3f, eIF3h and eIF3l highly were associated with the IDH mutant status of gliomas." (PMID 31171919, 2019). "Regarding the eIF3 complex, significantly higher protein expression in gliomas compared to CCBT was detected for eIF3B (III: p < 0.05), eIF3D (I: p < 0.05; III: p < 0.05), eIF3H (III: p < 0.05), eIF3I (I: p < 0.05, III: p < 0.001, IV: p < 0.01) and eIF3M (III: p < 0.01)." (PMID 33807050, 2021).
esophageal cancer (3 papers, 2020 to 2022). A primary or metastatic malignant neoplasm involving the esophagus. "EIF3H is significantly upregulated in esophageal cancer and functions as a novel deubiquitinating enzyme of Snail, driving aggressiveness and metastasis." (PMID 34820329, 2021). "We found that EIF3H is significantly upregulated in esophageal cancer and ectopic expression of EIF3H in ESCC cell lines promotes cell proliferation, colony formation, migration and invasion." (PMID 32867821, 2020). "And EIF3H can promote the Snail-mediated EMT process of esophageal cancer." (PMID 35664798, 2022). "In esophageal cancer, EIF3H interacts and stabilizes Snail through deubiquitination." (PMID 35664798, 2022). "We first analyzed the expression of EIF3H in esophageal cancer of TCGA data in UALCAN (n = 195)." (PMID 32867821, 2020).
lung carcinoma (3 papers, 2021 to 2024). "The interaction between METTL3 and eIF3h is essential for translation and oncogenic transformation in lung cancer." (PMID 34568001, 2021). "EIF3H subunits have been proved to physically and functionally interact with METTL3, which causes the translation of many oncogenic mRNA, including bromodomain-containing protein 4 which is modified by m6A in primary lung cancer." (PMID 36051357, 2022). "Several studies have already reported the harmful effect of high expression of EIF3 subunits in lung cancer, including EIF3C, EIF3D, and EIF3H." (PMID 36051357, 2022). "For instance, independent of m6A readers, METTL3 in human lung cancer can promote translation of a large subset of oncogenic mRNAs though recruiting eukaryotic translation initiation factor 3 subunit h (eIF3h)." (PMID 38545555, 2024).
Alzheimer disease (2 papers, 2021). A progressive, neurodegenerative disease characterized by loss of function and death of nerve cells in several areas of the brain leading to loss of cognitive function such as memory and language. "This learning-induced reduction in the level of eif3h was lost in a transgenic mouse model for Alzheimer’s disease which exhibited impaired learning/memory, suggesting that Eif3h may be involved in hippocampus-dependent learning and memory." (PMID 33441873, 2021).
breast tumor (2 papers, 2020 to 2025). "Moreover, Eukaryotic translation initiation factor 3 subunit H (EIF3H), a DUB and critical translational initiation factor, plays a major role in breast tumor invasion and metastasis by modulating the Hippo-YAP pathway." (PMID 33158118, 2020).
esophageal squamous cell carcinoma (2 papers, 2020 to 2025). Esophageal squamous cell carcinoma (ESCC) is a type of esophageal carcinoma (EC) that can affect any part of the esophagus, but is usually located in the upper or middle third. "Overexpression of eukaryotic translation initiation factor 3H (EIF3H) predicts cancer progression and poor prognosis, but the mechanism underlying EIF3H as an oncogene remains unclear in esophageal squamous cell carcinoma (ESCC)." (PMID 32867821, 2020). "Furthermore, USP26 108, PSMD14 121, OTUB1 117, and EIF3H 119 deubiquitinate and stabilize Snail, enhancing esophageal squamous cell carcinoma (ESCC) cell migration and tumor metastasis in vivo and in vitro." (PMID 41208892, 2025).
liver cancer (2 papers, 2010 to 2016). An epithelial or non-epithelial malignant neoplasm that arises from the liver. "Overexpression of EIF3H is seen in prostate, breast, and liver cancer and overexpression of eIF3h malignantly transforms immortal NIH-3T3 cells." (PMID 20862326, 2010).
pancreatic adenocarcinoma (2 papers, 2021 to 2026). "Through a series of correlation, expression, and survival analyses, we identified noncoding RNAs (ncRNAs) that contribute to the upregulation of EIF3H in pancreatic adenocarcinoma (PAAD)." (PMID 41822359, 2026).
viral infection (2 papers, 2025). "It has been shown in several studies that EIF3H is associated with viral infectious diseases, including rabies virus and hepatitis C virus (HCV)." (PMID 39965013, 2025). "Notably, the expression levels of the majority of these proteins increased following viral infection, with the exception of three proteins (Eif3h, Eif4h, and Csf1r), which exhibited downregulation." (PMID 40547011, 2025).
astrocytoma (1 paper, 2021). "Besides the already known eIFs, we demonstrated significantly elevated protein levels of eIF3D, eIF3H, eIF3I, eIF3M, p-eIF4G, eIF4H, eIF5 and eIF6 in astrocytoma tissue compared to CCBT." (PMID 33807050, 2021).
bladder cancer (1 paper, 2021). "PAG translocation (t8:8)(q21:q24) (EIF3H/PAG) was identified in several solid malignancies and among PAG variants, rs500315427 was strongly associated with severe prognosis in bladder cancer." (PMID 34083754, 2021).
colitis (1 paper, 2024). Inflammation of the colon. "Taken together, these data suggest that EIF3H deletion attenuates colitis-induced colorectal tumorigenesis." (PMID 38514606, 2024).
colon cancer (1 paper, 2024). "Upregulated EIF3H protein expression was observed in the Clinical Proteomic Tumor Analysis Consortium colon cancer database as well." (PMID 38514606, 2024).
colon tumors (1 paper, 2024). "Nonetheless, inducible heterozygous Eif3h knockout (Eif3hflox/wt, Villin-CreERT) mice develop less and smaller colon tumors compared with their wildtype littermates in the AOM/DSS model, suggesting the effect of Eif3h haploinsufficiency on tumorigenesis." (PMID 38514606, 2024). "We analyzed change in mRNA level of Eif3h from datasets of colon tumors isolated from ApcMin/+ and AOM-treated mice (GSE5204), and found that Eif3h mRNA level was elevated in tumors of ApcMin/+ and AOM-induced mice compared with normal mice colon tissues." (PMID 38514606, 2024).
endometrial cancer (1 paper, 2019). Primary or metastatic malignant neoplasm involving the endometrium (mucous membrane that lines the endometrial cavity). "We further investigated the expression patterns of peIF2α, eIF2α, eIF3c, eIF3h, eIF4e, eIF4g, eIF5 and eIF6 in endometrial cancer compared to non-neoplastic patient samples using immunoblot analysis." (PMID 31817792, 2019).
liver fibrosis (1 paper, 2023). "This led to the identification of several cis-eQTLs, including those for phosphatase and actin regulator 2 (Phactr2) and eukaryotic translation initiation factor 3 subunit H (Eif3h), the gene expression of which significantly correlated with liver fibrosis." (PMID 37000167, 2023).